RIPK1 (receptor interacting serine/threonine kinase 1)
Diseases named in the same sentence as RIPK1 in open-access papers (continued):
Sharing a sentence is not in itself a finding about the gene and the disease.
benign prostate hyperplasia (1 paper, 2017). "Expression of RIPK1 in prostate gland disease was higher in benign prostate hyperplasia and non-cancer tissue than the tumor component." (PMID 29050220, 2017). "In terms of tissue expression, RIPK1 levels were markedly higher in benign prostate hyperplasia and non-cancerous tissue regions relative to the tumor area." (PMID 29050220, 2017). "RIPK1 was enriched in benign prostate hyperplasia and non-tumor areas, but not the tumor area." (PMID 29050220, 2017).
bladder cancer (1 paper, 2015). "After its MCT1- and NHE1-directed entry in oncogenic H-Ras-transformed bladder cancer cells, 3-BrPA activates the PARP and RIPK3/MLKL/Drp1 necrotic axes, presumably together with the RIPK3/MLKL/TRPM7, RIPK3/MLKL/NHE1 and RIPK3/SAPK/JNK necrotic subroutines, in RIPK1-independent manner." (PMID 26198749, 2015).
brain cancer (1 paper, 2022). A primary or metastatic malignant neoplasm affecting the brain. "Although brain cancer grows in an acidic TME, the pH will fall gradually in tumor tissue, and it is unclear whether this would induce RIPK1-dependent cell death via activation of ASIC1a." (PMID 35961983, 2022).
breast invasive carcinoma (1 paper, 2025). "In 3 representative tumor types with high expression of SPOP and RIPK1, kidney renal clear cell carcinoma, liver hepatocellular carcinoma, and breast invasive carcinoma, this regulatory mechanism remains applicable." (PMID 41122967, 2025).
chronic hepatitis (1 paper, 2020). An active inflammatory process affecting the liver for more than six months. "Thus, RIPK1 autophosphorylation at S166 is essential for RIPK1 kinase activity-dependent hepatocyte apoptosis, chronic hepatitis and HCC development in NEMOLPC-KO mice." (PMID 32269263, 2020).
chronic lung disease (1 paper, 2020). According to the definitions of the American and British Thoracic Societies, including pulmonary functional tests, X-rays, and CT scans for items such as fibrosis, bronchiectasis, bullae, emphysema, nodular or lymphomatous abnormalities. "Programmed necrosis (necroptosis) is a cellular program regulated by RIPK1 (receptor-interacting protein kinase 1) and RIPK3, and MLKL (mixed lineage kinase domain-like pseudokinase) in chronic lung diseases." (PMID 32357474, 2020).
cyst (1 paper, 2021). A sac-like closed membranous structure that may be empty or contain fluid or amorphous material. "To exclude a proliferation-promoting function of RIPK1 as a crucial element for cyst formation, we examined the level of proliferation in the liver tissue of the different KO mice." (PMID 33798093, 2021). "In line with this, we showed that RIPK1 was overexpressed in the human cyst epithelium of a subset of patients with polycystic liver disease." (PMID 33798093, 2021). "Collectively, these data reveal a functional interaction between JNK signaling and RIPK1 in age-related progressive cyst development." (PMID 33798093, 2021). "In line with this, additional Caspase-8 deletion and concomitant apoptosis inhibition restored cyst formation (JNK1/2/RIPK1/Casp-8LPC-KO mice)." (PMID 33798093, 2021). "Mechanistically, we could show that cyst formation in livers of JNK1/2LPC-KO mice was dependent on receptor-interacting protein kinase 1 (RIPK1), a known regulator of cell survival, apoptosis, and necroptosis." (PMID 33798093, 2021). "This argues against a role of DNA-damage response in the RIPK1/CASPASE-8–dependent mediation of the cyst phenotype in JNK1/2LPC-KO mice, suggesting that a cell-death function of RIPK1 may be responsible for the phenotype." (PMID 33798093, 2021). "In order to test the functional interaction of RIPK1 with CASPASE-8 in cyst formation of JNK1/2LPC-KO mice, we intercrossed JNK1/2/RIPK1LPC-KO mice with Caspase-8FL mice (JNK1/2/RIPK1/CASP-8LPC-KO)." (PMID 33798093, 2021). "Interestingly, despite the rescue from cyst development, additional deletion of Ripk1 did not significantly alter ALT, GLDH, and AP serum levels but led to a significant reduction of the necrotic areas compared with JNK1/2LPC-KO animals, suggesting ameliorated but ongoing hepatocellular damage." (PMID 33798093, 2021). "While the additional deletion of Caspase-8 or Mlkl alone did not rescue the cyst phenotype in JNK1/2LPC-KO, additional deletion of Ripk1 prevented biliary cyst formation." (PMID 33798093, 2021).
cystadenoma (1 paper, 2025). A benign or borderline cystic epithelial neoplasm arising from the glandular epithelium. "Regarding TRAF2, RIPK1, TNFRSF10D/TRAIL-R4, and NF-ΚB, differential mRNA expression profiles were identified between the cystadenoma and EOC groups, with statistically significant differences observed between primary and metastatic EOC." (PMID 40943317, 2025).
cytomegalovirus infection (1 paper, 2021). A herpesvirus infection caused by Cytomegalovirus. "For example, TLR3-induced necroptosis in fibroblasts and endothelial cells did not require RIPK1 but involved both RIPK3 and MLKL, whilst necroptosis due to cytomegalovirus infection was RIPK1-independent but involved RIPK3 activity." (PMID 33925729, 2021).
diabetic nephropathy (1 paper, 2023). "It was speculated that high glucose-induced necroptosis mediated by TNF might be further regulated by ubiquitin carboxy-terminal hydrolase L1 (UCHL1) via the RIPK1/RIPK3 pathway, leading to enhanced progression of diabetic nephropathy and increased podocyte injury and loss." (PMID 36756299, 2023).
endometriosis (1 paper, 2025). The growth of functional endometrial tissue in anatomic sites outside the uterine body. "This study employed an integrative multi-omics approach to investigate Fas/RIPK1 pathway dysregulation in endometriosis (EMs)." (PMID 41341035, 2025). "However, in endometriosis (EMs), we observed significantly elevated expression levels of both Fas and RIPK1 compared with normal controls (CON)." (PMID 41341035, 2025).
endotoxemia (1 paper, 2023). "We found that O-GlcNAcylation of RIPK1 was decreased during LPS-induced endotoxemia and a reduction of RIPK1 O-GlcNAcylation was blocked by Thiamet-G (TMG), an OGA inhibitor." (PMID 37359541, 2023). "In this study, we suggest a molecular mechanism for erythrocyte necroptosis by LPS-induced endotoxemia, by elucidating that RIPK1 O-GlcNAcylation suppresses necroptosis signaling in erythrocytes." (PMID 37359541, 2023). "Therefore, to elucidate the molecular mechanism through which the reduced O-GlcNAcylation of RIPK1 during LPS-induced endotoxemia results in erythrocyte damage, we determined whether serine 166 of RIPK1 is also phosphorylated in erythrocytes." (PMID 37359541, 2023). "We confirmed that cellular O-GlcNAcylation levels and O-GlcNAcylation of RIPK1 were attenuated by TSZ treatment, as was the case when necroptosis was induced in erythrocytes by in vivo LPS-induced endotoxemia." (PMID 37359541, 2023).
enteropathy (1 paper, 2025). "Here, we demonstrate that RIPK1 deficiency in conventional T cells leads to a complex enteropathy driven by both microbiome-dependent and independent pathology." (PMID 40307618, 2025).
Flavivirus Infections (1 paper, 2022). Infections with viruses of the genus FLAVIVIRUS, family FLAVIVIRIDAE. "RIPK1 plays a protective role against flavivirus infections." (PMID 36310878, 2022).
gallbladder carcinoma (1 paper, 2020). "In contrast, silencing of RIPK1 expression inhibits invasion in gallbladder carcinoma, therefore RIPK1 might act as a double-edged sword in cancers." (PMID 33036630, 2020).
Glucose intolerance (1 paper, 2024). Glucose intolerance (GI) can be defined as dysglycemia that comprises both prediabetes and diabetes. "In diabetic mice, RIP1 expression is increased in liver, adipose tissue, and muscle, and targeting RIPK1 with a specific inhibitor, necrostatin-1 (Nec-1), prevents insulin resistance and glucose intolerance, independent of its effect on inflammation." (PMID 38195700, 2024).
H1N1 virus infection (1 paper, 2024). "H1N1 virus infection significantly increased RIPK1S321 phosphorylation, leading to the upper shift of the RIPK1 band in L929 cells, a phenomenon also observed by others." (PMID 39044278, 2024). "RIPK1 knockout did not significantly change the level of ZBP1 expression in the clone used here in the absence or presence of H1N1 virus infection at multiple time points." (PMID 39044278, 2024).
Hodgkins lymphoma (1 paper, 2023). A heterogeneous group of malignant lymphoid neoplasms of B-cell origin characterized histologically by the presence of Hodgkin and Reed-Sternberg (HRS) cells in the vast majority of cases. "Then, we knock down the expression of RIPK1 in GM12878 (a normal human B lymphocyte cell line) and L428 (a Hodgkin's lymphoma cell line with a relatively high expression of RIPK1) cells using the shRNA vector." (PMID 37462822, 2023).
Hyperammonemia (1 paper, 2025). An increased concentration of ammonia in the blood. "In the present study, hyperammonemia was associated with increased hepatic expression of both RIPK1 and RIPK3." (PMID 40053595, 2025). "In conclusion, hyperammonemia induces liver fibrogenesis and RIPK1-mediated cell death, which is associated with urea cycle dysfunction." (PMID 40053595, 2025). "Inhibition of RIPK1 with its selective inhibitor RIPA-56 protected against hyperammonemia and restored RIPK3 protein expression levels and prevented liver cell death and fibrogenesis." (PMID 40053595, 2025). "Hyperammonemia induces liver injury, which can be prevented by inhibiting the Toll-like receptor 4 and RIPK1 pathway." (PMID 40053595, 2025). "On the basis of the finding that hyperammonemia induces increased expression of the necroptosis proteins RIPK1 and RIPK3, we aimed at assessing whether inhibition of this pathway would protect against hyperammonemia-induced liver injury and further hyperammonemia." (PMID 40053595, 2025). "Inhibition of receptor-interacting serine/threonine-protein kinase 1 (RIPK1) and its upstream inducer Toll-like receptor 4 (TLR4) protected against liver injury and further hyperammonemia." (PMID 40053595, 2025). "Inhibition of RIPK1 and TLR4 protects against hyperammonemia-induced liver injury and are potential therapeutic targets for hyperammonemia and chronic liver disease progression." (PMID 40053595, 2025).
Hypercholesterolemia (1 paper, 2021). An increased concentration of cholesterol in the blood. "In summary, we report a stage-dependent effect of RIPK1 inhibition in atherogenesis under two most common risk factors—hypercholesterolemia and hypertension." (PMID 34760938, 2021). "To examine the effect of RIPK1 inhibition on the development of advanced atherogenesis, we used a mouse model (ApoESA/SA) that exhibits both hypercholesterolemia and hypertension upon induction and develop advanced atherosclerotic lesions including those in coronary arteries." (PMID 34760938, 2021). "Approach and Results: To investigate the effect of RIPK1 inhibition in advanced atherosclerotic plaque formation, we used ApoESA/SA mice, which exhibit hypercholesterolemia, and develop angiotensin-II mediated hypertension upon administration of doxycycline in drinking water." (PMID 34760938, 2021).
Infertility (1 paper, 2020). "Specifically, excessive TNF-α binds to its receptor (TNFR) on the granulosa cell and oocyte membranes, which triggers necroptosis through the receptor interacting protein kinase-1 (RIPK1)-mediated pathway, and ultimately may cause follicular atresia and infertility." (PMID 33050936, 2020).
Insulin resistance (1 paper, 2024). Increased resistance towards insulin, that is, diminished effectiveness of insulin in reducing blood glucose levels. "This high expression may be mediated through receptor-interacting protein kinase 1 (RIPK1), suggesting mitochondrial dysfunction, increased ROS production, and increased insulin resistance." (PMID 38880916, 2024).
intervertebral disc degeneration (1 paper, 2019). "Short hairpin RNAs for receptor interacting serine/threonine kinase 1 (RIPK1) were constructed to examine the effects of RIPK1 knockdown in primary chondrocyte cells and in animal models of caudal vertebra intervertebral disc degeneration in vivo." (PMID 31029152, 2019). "Animal models of caudal vertebra intervertebral disc degeneration further demonstrated that apoptosis was induced by up-regulation of tumor necrosis factor (TNF) accompanied by down-regulation of NF-κB and MAPKs cascades that are dependent on caspase and RIPK1." (PMID 31029152, 2019).
keloid (1 paper, 2022). An irregularly shaped, elevated mark on the skin caused by deposits of excessive amounts of collagen during wound healing. "Compared with normal skin fibroblasts, there were more TUNEL staining-positive cells, higher RIPK1 and RIPK3 expressions as well as MLKL phosphorylation in keloid fibroblasts (P < 0.01), which were all reversed by NaHS pretreatment (P < 0.01)." (PMID 35774378, 2022).
listeriosis (1 paper, 2021). A bacterial infection caused by Listeria monocytogenes. "RIPK1 immunoprecipitates from livers of both mouse strains contained RIPK3 with an increased amount in OTUB1LPC-KO mice indicating that OTUB1-deficiency increases necroptosis during listeriosis." (PMID 33712742, 2021). "So far it has been exemplified in listeriosis, that infected Kupffer cells undergo RIPK1/MLKL-dependent necroptosis, whereas hepatocytes may become apoptotic [11, 12 and this study]." (PMID 33712742, 2021). "In vivo, the critical function of the RIPK1 kinase activity for the exacerbation of listeriosis in OTUB1LPC-KO mice is illustrated by the reduction of hepatocyte damage, cell death and prevention of lethal listeriosis upon inhibition of RIPK1 kinase activity by Nec-1s." (PMID 33712742, 2021).
liver dysfunction (1 paper, 2025). "By doing so, patient populations most likely to benefit can be identified while avoiding severe toxicity in susceptible individuals (e.g., those with liver dysfunction), thus increasing the success rate of clinical trials and uncovering the true clinical value of RIPK1 targeting." (PMID 41334873, 2025).
liver neoplasm (1 paper, 2021). Tumors or cancers of the LIVER. "Given that RIPK1 was significantly downregulated in Huh-7 (R) and HCCLM3 (R) cells, next, ENCORI and TargetScan 7.2 were used to analyze miRNAs that might bind to CASC2 and RIPK1; moreover, HMDD v3.2 data were used to analyze miRNAs that might relate to liver neoplasms." (PMID 35145900, 2021).
lupus nephritis (1 paper, 2016). Glomerulonephritis in the context of systemic lupus erythematosus. "In contrast, in the kidney, the expression of genes involved in pyroptosis, e.g. NLRP3 and CASP1 were significantly increased and TNFR1, RIPK1, RIPK3, CIAP1/2 and GPX4 were significantly decreased along the progression of lupus nephritis (LN)." (PMID 27811014, 2016).
malnutrition (1 paper, 2024). Inadequate nutrition resulting from poor diet, malabsorption, or abnormal nutrient distribution. "Here, we discuss an infant with malnutrition, VEO-IBD, recurrent infections and polyathritis who has a homozygous partial deletion in RIPK1 gene." (PMID 38676845, 2024).
motor neuron disease (1 paper, 2020). "Importantly, the deletion of mitochondria/ER-associated innate immunity coordinators like STING or cytosolic immunity sensors like RIPK1 can prevent neurodegenerative processes in PD and the motor neuron disease ALS." (PMID 32342250, 2020).
Myocardial fibrosis (1 paper, 2022). "We found that HGF induced myocardial fibrosis and cardiac dysfunction, which corresponded to RIPK1/RIPK3 activation and up-regulation of autophagic related proteins in both in vitro and in vivo models." (PMID 35165268, 2022). "We hypothesized that RIPK1/RIPK3 activation mediated myocardial fibrosis by impairing the autophagic flux." (PMID 35165268, 2022).
myonecrosis (1 paper, 2018). "In TAs of 2-week-old mdx mice (i.e., before the onset of myonecrosis), the levels of Ripk1, Ripk3, and Mlkl transcripts were similar to those in TAs from C57BL/10 controls." (PMID 30194302, 2018).
neuropathy (1 paper, 2022). A disorder affecting the nervous system that manifests with pain, tingling, numbness, and/or muscle weakness. "In contrast to apoptosis, necrosis depends on the participation of receptor-interacting protein kinase 1 (RIP1/RIPK1) and receptor-interacting protein 3 (RIP3) and is related to many pathological conditions such as AP, ischaemia–reperfusion injury and neuropathy." (PMID 35509084, 2022).
nonalcoholic fatty liver (1 paper, 2022). "Moreover, liver-specific SENP1 knockout exaggerates hepatic inflammation and liver damage in high-fat-diet (HFD)-induced nonalcoholic fatty liver, which is suppressed by RIPK1-D138N mutation." (PMID 36414671, 2022). "Notably, genetic inhibition of RIPK1 effectively reverses disease progression in hepatocyte-specific SENP1-knockout male mice with high-fat-diet-induced nonalcoholic fatty liver." (PMID 36414671, 2022).
peripheral nerve injury (1 paper, 2022). Injury to a peripheral nerve. "The top-ranked signaling analysis enrichment of sequencing has shown that several down-stream signaling of RIPK1, including NF-κB signaling, MAPK signaling has been activated after peripheral nerve injury." (PMID 36438920, 2022).
pharyngeal carcinoma (1 paper, 2021). "Expression of FADD and RIPK1 in different groups of hypo pharyngeal carcinoma." (PMID 34262870, 2021).
polycystic kidney (1 paper, 2021). "Inhibition of RIPK1, however, did not affect the polycystic kidney development, dwarfism, or facial deformity in this mutant line." (PMID 34376696, 2021).
polycystic liver diseases (1 paper, 2021). "The specific overexpression of RIPK1 in cysts of a subset of patients with polycystic liver disease suggests that RIPK1 might be mechanistically involved in the pathogenesis of human biliary cysts." (PMID 33798093, 2021).
prion disease (1 paper, 2024). A transmissible disease that is caused by a protein that is able to induce abnormal folding of normal cellular proteins, leading to characteristic spongiform brain changes, which are associated with neuronal loss without an inflammatory response. "The observed increase in RIPK1 might associate with TNFα-TNFR1, enhancing microgliosis, a prominent neuropathology in prion disease." (PMID 38802941, 2024). "Interestingly, not a single study so far has focused into the crucial role of TRADD, TRAF2, FADD, and RIPK1 in prion diseases." (PMID 38802941, 2024). "Similarly restoring RIPK1, TRADD and TRAF2 expression would be direct clinical implications on prion diseases." (PMID 38802941, 2024). "The upregulated Fas, FasL, and RIPK1, alongside reduced TRADD levels, may account for the pronounced microgliosis observed in this prion disease mouse model." (PMID 38802941, 2024).
Psoriasiform dermatitis (1 paper, 2021). A skin abnormality characterized by redness and irritation, with thick, red skin that displays flaky, silver-white patches (scales). "Inhibition of RIPK1 or MLKL could reduce inflammation of psoriasiform dermatitis in mice." (PMID 34977874, 2021). "Inhibition of RIPK1 or MLKL could attenuate necroptosis both in vitro and in vivo, and powerfully reduce inflammation in psoriasiform dermatitis mice induced by IMQ." (PMID 34977874, 2021).
ptosis (1 paper, 2022). The drooping of the upper eyelid. "The multi-targeted kinase inhibitor Ponatinib, as an antitumor agent, can also prevent necrotic ptosis by targeting RIPK1, but its lack of specificity and severe long-term adverse reactions have limited its development for the treatment of inflammatory diseases associated with RIPK1." (PMID 36249746, 2022).